INS (insulin)
Diseases named in the same sentence as INS in open-access papers (continued):
Sharing a sentence is not in itself a finding about the gene and the disease.
Insulin resistance (continued). "Serum levels of insulin were significantly higher in HFD‐fed WT mice than in bid−/− mice, suggesting a milder insulin resistance in the latter, which was confirmed by the insulin tolerance test (ITT)." (PMID 36382356, 2022). "We found that blood glucose levels, after insulin injection, were higher in HFD Ni mice when compared to HFD Hp group, which suggested that the infection prevented the development of peripheral insulin resistance." (PMID 35499991, 2022). "Insulin resistance is the link between obesity and T2DM and is characterized as a blunted response of insulin tissue targets to insulin that, in concert with impaired pancreatic β-cell dysfunction, contributes to hyperglycemia." (PMID 35208623, 2022). "Insulin resistance is usually determined based on HOMA-IR and QUICKI, whereas insulin secretion is determined based on HOMA-B." (PMID 35057420, 2022). "After 12 weeks of feeding, the mice in the HFFD group developed hyperinsulinemia, and the fasting insulin values were strikingly boosted (p < 0.01), indicating that HFFD induced insulin resistance in mice." (PMID 35407029, 2022). "Finally, insulin sensitivity, as a sensitive marker, was not measured, so we could not detect the association between protein food group consumption and the risk of insulin resistance." (PMID 35845792, 2022). "Each of these models exhibits insulin resistance and impaired glucose metabolism, which was demonstrated by a glucose tolerance test (GTT) and insulin tolerance test (ITT), and systemic inflammation characterized by elevated plasma IL-6 and TNF-α levels." (PMID 35327570, 2022). "Fasting plasma glucose (FPG), fasting insulin (FINS), glycated hemoglobin A1 (HbA1C), homeostasis model assessment-insulin sensitivity (HOMA-IS), and homeostasis model assessment-insulin resistance (HOMA-IR) were the main metformin efficacy measurements." (PMID 36289808, 2022). "Although the etiology of hepatic insulin resistance in obesity is complicated and not fully understood, research over the last decade has demonstrated how excessive SFA intake can impair insulin signaling and result in T2DM." (PMID 35328400, 2022). "Palmitic acid can impair the insulin signaling pathway, IRS/P13K/Akt, promoting IR, IRS-1, and Akt ubiquitination and subsequent protein degradation, leading to insulin resistance." (PMID 36035400, 2022). "The level of insulin was high in the HFD obese groups, which indicates that the high level of glucose present in the body is due to insulin resistance in rats." (PMID 35204193, 2022). "As insulin resistance is seen as a hallmark of schizophrenia, it is an interesting possibility that insulin levels or lack of responsiveness to insulin levels could be affecting the function of the sympathetic nervous system and contributing to symptoms in schizophrenia patients." (PMID 35844244, 2022). "Both hyperglycaemia and insulin resistance can downregulate IRS-1, which is a pivotal intermediary in insulin/IGF-1 signalling." (PMID 36035124, 2022). "FINS and HOMA-IR results showed that the serum INS level in T2DM group was significantly higher than that of control group, while the insulin resistance index was significantly increased." (PMID 35845591, 2022). "Due to the existence of insulin resistance in T2DM, IGF-1 and insulin are at a high level over a long period of time, with secondary elevation in IGF-1R." (PMID 35035440, 2022). "CR rats presented a lower body weight gain, lower fasting insulin, and lower HOMA-IR value when compared to controls, compatible with decreased insulin resistance." (PMID 36289871, 2022). "Increased PRLR expression in the hypothalamus stimulates whole body insulin sensitivity, whereas reduced PRLR expression results in insulin resistance and glucose intolerance." (PMID 36213259, 2022).
Insulin resistance (continued). "The homeostasis model assessment estimated insulin resistance (HOMA-IR) index is used to evaluate β-cell function and insulin resistance (IR), but the effectiveness of HOMA-IR is influenced by insulin treatment." (PMID 36698933, 2022). "The fasting surrogate measures include the homeostatic model assessment for insulin resistance (HOMA-IR), the quantitative insulin sensitivity check index (QUICKI), and fasting insulin." (PMID 35631177, 2022). "Of note, since TyGIS has been built as marker of insulin sensitivity (direct predictor of PREDIM), whereas TyG is a possible marker of insulin resistance, OR value was lower than 1 for TyGIS and higher than 1 for TyG." (PMID 36258194, 2022). "When we performed quantitative insulin-sensitivity check index (QUICKI) analysis, this was significantly reduced in AAV-EGFP mice compared with WT mice, indicative of insulin resistance." (PMID 36320417, 2022). "Moreover, a condition of chronic low-grade inflammation may impair insulin sensitivity; insulin resistance worsens the inflammatory state, increasing abdominal obesity, intrahepatic fat stocking, vascular inflammation and endothelial dysfunction, which leads to an increase in cardiovascular risk." (PMID 36296979, 2022). "We evaluated fasting insulin resistance (IR) with the homeostatic model of insulin resistance (HOMA-IR) and estimated the Matsuda insulin sensitivity index (ISI) and insulin secretion with an oral glucose tolerance test." (PMID 35725477, 2022). "In order to verify if honey ingestion also improves central insulin resistance, we investigated the effects of HFD and honey supplementation on insulin signaling in the brain." (PMID 35215406, 2022). "This study is the first RCT to investigate the effect of mHealth-based home exercise with a wrist-wearable device on insulin sensitivity, physical fitness, and quality of life for HCC patients with insulin resistance." (PMID 36348422, 2022). "In the present study, insulin resistance increased with increasing O2·− in WT with HFHSD, while in SOD1−/− with HFHSD, insulin secretion decreased and insulin resistance instead improved." (PMID 35883894, 2022). "This pollutant can deregulate the metabolism of the entire organism, promoting the development of obesity, insulin resistance, dyslipidemia, hypertension, atherosclerosis, NAFLD while impairing insulin secretion." (PMID 35651975, 2022). "In male C57B6/J mice, Aroclor-1254 induced adiposity and insulin resistance and resulted in a significant increase in FBG, insulin, HOMA-IR, TG, FFA and TC." (PMID 35276982, 2022). "Valine and Isoleucine significantly reduced fasting insulin concentrations compared to FFD, indicative of a BCAA‐induced improvement in insulin resistance." (PMID 35830259, 2022). "3T3-L1 Adipocytes-derived miR-27a has been shown to induce insulin resistance in C2C12 cells by targeting PPARγ, a potent modulator of whole-body lipid metabolism and insulin sensitivity." (PMID 36293266, 2022). "The gradation of insulin resistance was determined by HOMA-IR and was calculated from the fasting plasma glucose and insulin levels." (PMID 36290804, 2022). "Together, these data show that palmitate inhibits insulin-induced formation of endogenous IRS1 condensates, which is in parallel with the development of insulin resistance in cells." (PMID 35790738, 2022). "At the same time point, we also observed a significant increase in insulin levels, which translates into an increase in the HOMA-IR ratio indicative of a state leading to peripheral insulin resistance." (PMID 35563135, 2022). "As with typical insulin resistance, PCOS-related insulin resistance is characterized by reduced sensitivity and responsiveness to insulin-mediated glucose utilization primarily in skeletal muscle and adipose tissue." (PMID 36457554, 2022).
Insulin resistance (continued). "Consistent with this, patients with IGF-1 gene deletion exhibit severe insulin resistance, and mice with IGF-1 deletion in the liver exhibit insulin resistance and administration of IGF-1 improved the insulin-resistant state." (PMID 35745205, 2022). "It was reported that apomorphine improved memory function, reduced insulin resistance, and increased IDE levels in 3×Tg-AD mice by stimulating insulin signaling." (PMID 35457168, 2022). "In a large, multi-ethnic and prospective cohort study of more than 15,000 postmenopausal women published in Circulation: Cardiovascular Quality and Outcomes, insulin levels, HOMA-IR, blood glucose, and TG/HDL-C were measured to assess insulin resistance." (PMID 36438585, 2022). "Values of fasting serum insulin, C-reactive protein (CRP), and indicators of insulin resistance were higher in the affected individuals." (PMID 35206286, 2022). "Rats in the HFD group had higher values of fasting blood glucose, fasting insulin, and HOMA-IR index compared with those in the control group (all P < 0.01), indicating that there was a significant insulin resistance in MS rats." (PMID 36109620, 2022). "Treatment with obese ATM-derived exosome leads to insulin resistance, whereas lean ATM-derived exosome increases insulin sensitivity in obese mice." (PMID 36119080, 2022). "When glucose and insulin were used to calculate HOMA-IR, this measure of insulin resistance was also significantly lower in WM rats compared to AdLib controls." (PMID 35725493, 2022). "In this sense, several clinical trials have suggested that RV increases insulin sensitivity and decreases blood glucose levels in subjects with T2DM, and the same effect has been observed in subjects with insulin resistance." (PMID 36014469, 2022). "The most commonly used is the homeostatic model of insulin resistance (HOMA-IR), which is based on fasting insulin and glucose values." (PMID 36419920, 2022). "Here the authors report that insulin-dependent dephosphorylation stabilizes ERRα via the GSK3β/FBXW7 axis, and disruption of this post-translational mechanism results in insulin resistance in mice." (PMID 35440636, 2022). "Given that PAK1 depletion in mouse skeletal muscle leads to insulin resistance and glucose intolerance, we sought to examine if PAK1 enrichment would promote insulin sensitivity and enhance glucose tolerance." (PMID 35222279, 2022). "Insulin resistance (HOMA-IR) and insulin sensitivity (Matsuda index) after intake of granola with cereal beta-glucan in different amounts." (PMID 35578615, 2022). "WT showed insulin resistance and elevated blood glucose in HFHSD, while SOD1−/− showed decreased insulin secretion and elevated blood glucose." (PMID 35883894, 2022). "Surrogate markers of insulin resistance (higher HOMA IR, lower QUICKI, higher fasting insulin concentrations) were lower in women carrying male fetuses than in those carrying females." (PMID 35509032, 2022). "Separately, it has been reported that HFD-induced exosome-derived phosphatidylcholine binds to and activates AhR, to inhibit the insulin signaling pathway and induce HFD-mediated insulin resistance." (PMID 36499198, 2022). "High PGD2 levels have been shown to enhance insulin sensitivity, and KD of PTGDS results in an opposite effect resulting in insulin resistance, but also nephropathy and atherosclerosis." (PMID 35948367, 2022). "In light of the profound changes in insulin levels, the HOMA-IR index for insulin resistance was also increased only in HFD-fed mice, while it remained unchanged when this diet also contained C. iphionoides." (PMID 36364811, 2022). "This is the first study to suggest that 17β‐estradiol replacement improves high‐fat diet‐induced insulin resistance, and this effect is accompanied by the alterations in the Akt2 and AS160 phosphorylation in insulin‐stimulated muscles of ovariectomized rats." (PMID 35238495, 2022).
Insulin resistance (continued). "QUICKI quantitative insulin sensitivity check, oDIcpep oral disposition index, HOMA-IR homeostasis model assessment for estimating insulin resistance, HOMA-%B homeostasis model assessment for estimating β-cell function." (PMID 36028540, 2022). "To induce insulin resistance in vitro, we treated IHH hepatocytes with high concentrations of insulin." (PMID 36072934, 2022). "Insulin resistance was found to be a precursor to neurodegeneration in T2DM, which can be mimicked in zebrafish larvae induced with high insulin." (PMID 35955446, 2022). "Omega-3 supplementation was additionally found to trigger an increase in insulin sensitivity as measured by QUICKI (Quantitative Insulin Sensitivity Check Index) and HOMA-IR (Homeostatic Model Assessment of Insulin Resistance)." (PMID 36142215, 2022). "The genistein group had significantly lower levels of serum insulin, MDA, TNF-α, IL-6, and improved insulin resistance, as well as reduced waist to hip ratio, body fat percentage and triglyceride compared to the placebo." (PMID 35678936, 2022). "Increased PRLR expression in liver stimulates both liver and systemic insulin sensitivity, whereas reduced hepatic PRLR expression results in tissue and whole-body insulin resistance." (PMID 36213259, 2022). "The quantitative assessment of insulin resistance (HOMA-IR) and insulin production/β-cell function (HOMA-β) are vital keys for measuring IR and assessing β-cell function." (PMID 35190649, 2022). "The most frequently used IR indicator in clinical and epidemiological studies is the homeostatic model assessment for insulin resistance (HOMA-IR), which is based on an insulin assay." (PMID 35370984, 2022). "Other anti-diabetic drugs including insulin could also have a benefit on muscle mass and function, but there have been no studies to date supporting this hypothesis among older adults, particularly on account of the supposed effect of age-related insulin resistance." (PMID 35267412, 2022). "In the current study, PCOS patients had significantly higher levels of fasting insulin and HOMA-IR when compared to controls (P < 0.05 for both), indicating a degree of insulin resistance." (PMID 35700181, 2022). "Insulin resistance test (ITT) results also showed that HFD mice were with lower insulin sensitivity and were easier to develop hyperinsulinemia than STD mice." (PMID 36263377, 2022). "Insulin resistance is a main determinant of such events, as TAG/free fatty acid (FFA) flux is controlled by the cellular insulin response, with the liver as a major insulin-responsive organ." (PMID 36499091, 2022). "Consistent with the results of glucose tolerance, the fasting serum insulin level and HOMA-IR index of the offspring in the HF group were significantly higher than those in the C group (p < 0.05), revealing insulin resistance." (PMID 35299765, 2022). "Considering the number of functions that insulin presents within the vascular endothelium (e.g., NO/ET-1 regulation), it is possible that insulin resistance observed following inactivity protocols might be a mechanism by which insulin resistance mediates inactivity-induced endothelial dysfunction." (PMID 36237532, 2022). "Insulin sensitivity marker, QUICKI, was lower in GA + AA compared to the GG group (0.326 ± 0.02 vs. 0.331 ± 0.02, p = 0.056), and insulin resistance marker HOMA was elevated (2.74 ± 1.55 vs. 3.17 ± 1.75; p = 0.04) in variant allele carrier GA + AA genotype." (PMID 36011374, 2022). "Excessive ROS production in mitochondria can induce insulin resistance by decreasing GLUT4 levels, inducing beta-cell and mitochondrial dysfunction, promoting inflammation, and inhibiting insulin signaling pathways." (PMID 35013137, 2022). "This was accompanied by a reduction in fasting insulin level in obese AKO mice, suggesting that adipocyte-restricted depletion of lactate protects mice from HFD-evoked insulin resistance." (PMID 36064857, 2022).
Insulin resistance (continued). "In the NutriTech study, insulin sensitivity status is determined by HOMA-IR, a surrogate index for whole-body insulin resistance." (PMID 36281448, 2022). "Changes in glycemic control can be expressed as a product of glucose and insulin, HbA1C (as an indicator of chronic glucose change) or by presenting as a HOMA-IR (homeostatic model of insulin resistance)." (PMID 36012550, 2022). "◊Although metformin has traditionally been used for treatment of insulin resistance in PCOS patients, its low therapeutic effectiveness as suggested by various studies brings in the novel role of other insulin sensitizers into play." (PMID 36518222, 2022). "The Nutrition to Optimize, Understand, and Restore Insulin Sensitivity in HIV for Oklahoma (NOURISH-OK) will use a novel, multi-level, integrated framework to explore how food insecurity contributes to insulin resistance among PLWH." (PMID 36225538, 2022). "Consistent with prevailing insulin resistance after HFD exposure, fasting serum insulin levels for these mice were markedly higher for Ad-Tmem120a−/− than control littermates." (PMID 35027552, 2022). "Previously, a study reported that celecoxib improved insulin sensitivity and showed efficacy in NAFLD mice with insulin resistance." (PMID 35713152, 2022). "In addition to the role of these conditions in creating insulin resistance and increasing signaling through the insulin and IGF-1R pathways, elevated glucose levels themselves may contribute to the EMT of endometrial through other, often interrelated, mechanisms." (PMID 36052252, 2022). "Palmitic acid induces insulin resistance in HEPG2 cells through enhanced ubiquitination and proteasomal degradation of key insulin signalling molecules." (PMID 36291085, 2022). "In the present study, we observed similar results, where RHSL restored blood insulin concentrations, meaning that RHSL has the potential to reverse the STZ-induced insulin resistance in C57BL/J6 mice." (PMID 36295866, 2022). "Homeostasis model assessment of insulin resistance (HOMA-IR) is computed with the following formula: HOMA-IR = fasting plasma glucose (FPG, mg/dL) × immunoreactive insulin (IRI, μIU/mL)/405." (PMID 35725822, 2022). "However, this significantly elevated fT3 concentration was found in subpopulations of women with significantly elevated 120 min 75 OGTT insulin, which reflects the results of other studies, suggesting that fT3 could be an indicator of insulin resistance development." (PMID 35329880, 2022). "Homeostasis model assessment-insulin resistance (HOMA-IR) and other indices calculated from fasting glucose and insulin were used to measure insulin resistance." (PMID 36699018, 2022). "Studies have shown that human-to-mice BAT transplantation results in increased insulin sensitivity, decreased body weight gain, and attenuated high fat diet (HFD)-induced insulin resistance." (PMID 35757435, 2022). "An early study found that insulin resistance in GDM patients led to a compensatory increase of the synthesis and secretion of insulin, which can promote the absorption and metabolism of blood glucose in islet β-cells." (PMID 35606885, 2022). "Suppression of autophagy-related gene 7 (ATG7) impairs insulin signaling, whereas restoration of ATG7 expression improves insulin resistance." (PMID 36499655, 2022). "IPITT results revealed systemic insulin resistance, indicating that animals in the AD-CON group had impaired systemic insulin sensitivity compared to those in the CON, AD-CS, and AD-FF groups." (PMID 35076339, 2022). "IRAK-M andmetabolic parameters, including fasting insulin (FINS), glycosylatedhemoglobin (HbA1c), homeostasis model assessment of insulin resistance(HOMA-IR) and beta-cell function (HOMA-β), and thioredoxin-interactingprotein (TXNIP), were evaluated." (PMID 36039603, 2022). "Insulin resistance was estimated by homeostasis model of insulin resistance (HOMA-IR) and the insulin sensitivity index (ISI)." (PMID 35085102, 2022).